ARHGEF2 (Rho/Rac guanine nucleotide exchange factor 2)
Description:
Activates Rho-GTPases by promoting the exchange of GDP for GTP. May be involved in epithelial barrier permeability, cell motility and polarization, dendritic spine morphology, antigen presentation, leukemic cell differentiation, cell cycle regulation, innate immune response, and cancer. Binds Rac-GTPases, but does not seem to promote nucleotide exchange activity toward Rac-GTPases, which was uniquely reported in PubMed:9857026. May stimulate instead the cortical activity of Rac. Inactive toward CDC42, TC10, or Ras-GTPases. Forms an intracellular sensing system along with NOD1 for the detection of microbial effectors during cell invasion by pathogens. Required for RHOA and RIP2 dependent NF-kappaB signaling pathways activation upon S.flexneri cell invasion. Involved not only in sensing peptidoglycan (PGN)-derived muropeptides through NOD1 that is independent of its GEF activity, but also in the activation of NF-kappaB by Shigella effector proteins (IpgB2 and OspB) which requires its GEF activity and the activation of RhoA. Involved in innate immune signaling transduction pathway promoting cytokine IL6/interleukin-6 and TNF secretion in macrophage upon stimulation by bacterial peptidoglycans; acts as a signaling intermediate between NOD2 receptor and RIPK2 kinase. Contributes to the tyrosine phosphorylation of RIPK2 through Src tyrosine kinase leading to NF-kappaB activation by NOD2. Overexpression activates Rho-, but not Rac-GTPases, and increases paracellular permeability (By similarity). Involved in neuronal progenitor cell division and differentiation. Involved in the migration of precerebellar neurons (By similarity).
Synonyms: GEF-H1; KIAA0651; LFP40; P40; Lfc; GEFH1; GEF; NEDMHM
Tractability: Small molecule: a structure with a bound ligand is known. Antibody: its Gene Ontology location is reachable by antibodies, with medium confidence. PROTAC: ubiquitination databases record sites on it; its protein half-life has been measured.
Gene: Protein-coding gene on chromosome 1 (155,946,851 to 156,007,070, reverse strand). Ensembl gene ENSG00000116584.
Subcellular location: Cytoplasm, cytoskeleton; Cytoplasm; Cell junction, tight junction; Golgi apparatus; Cytoplasm, cytoskeleton, spindle; Cell projection, ruffle membrane; Cytoplasmic vesicle
Pathways (Reactome):
Signal Transduction: G alpha (12/13) signalling events; NRAGE signals death through JNK; RHOA GTPase cycle; RHOB GTPase cycle
Gene Ontology:
Molecular function: guanyl-nucleotide exchange factor activity; microtubule binding; protein binding; small GTPase binding; zinc ion binding
Biological process: actin filament organization; asymmetric neuroblast division; cell morphogenesis; cellular response to muramyl dipeptide; negative regulation of microtubule depolymerization; positive regulation of interleukin-6 production; positive regulation of neuron differentiation; positive regulation of transcription by RNA polymerase II; positive regulation of tumor necrosis factor production; cellular hyperosmotic response; cellular response to tumor necrosis factor; intracellular protein transport; negative regulation of extrinsic apoptotic signaling pathway via death domain receptors; negative regulation of intrinsic apoptotic signaling pathway in response to osmotic stress; negative regulation of necroptotic process; positive regulation of neuron migration; regulation of cell population proliferation; regulation of Rho protein signal transduction; regulation of small GTPase mediated signal transduction; small GTPase-mediated signal transduction; establishment of mitotic spindle orientation; negative regulation of neurogenesis
Cellular component: cytoplasm; cytoplasmic vesicle; cytoskeleton; focal adhesion; Golgi apparatus; microtubule; protein-containing complex; ruffle membrane; vesicle; cytosol; bicellular tight junction; dendritic shaft; neuronal cell body; podosome; postsynaptic density; spindle
Genetic constraint (gnomAD): Loss-of-function variants: 22 observed, 121.15 expected, observed/expected ratio (o/e) 0.18, 90% interval 0.13 to 0.26. The upper end of that interval is the gene's LOEUF score, 0.26, which puts it in group 1 of 6, group 1 being the genes least tolerant of losing a copy. Missense variants: 907 observed, 1,346.2 expected, observed/expected ratio (o/e) 0.67, 90% interval 0.64 to 0.71. Synonymous variants: 487 observed, 534.91 expected, observed/expected ratio (o/e) 0.91, 90% interval 0.84 to 0.98.
Homologues: Orthologues: chimpanzee ARHGEF2 (97% identical), macaque ARHGEF2 (97% identical), guinea pig ARHGEF2 (95% identical), pig ARHGEF2 (94% identical), rabbit ARHGEF2 (94% identical), dog ARHGEF2 (92% identical), rat Arhgef2 (88% identical), mouse Arhgef2 (87% identical), tropical clawed frog arhgef2 (61% identical), zebrafish arhgef2a (51% identical), zebrafish arhgef2b (48% identical), Drosophila melanogaster cyst (23% identical), and 3 more. Paralogues in human: ARHGEF28 (33% identical), ARHGEF18 (32% identical), ARHGEF11 (17% identical), ARHGEF12 (17% identical), ARHGEF1 (15% identical), PLEKHG6 (14% identical), ARHGEF3 (10% identical), NET1 (10% identical).
Diseases named in the same sentence as ARHGEF2 in open-access papers:
ARHGEF2 is named in the same sentence as 73 diseases in open-access papers, as found by Europe PMC text mining. Sharing a sentence is not in itself a finding about the gene and the disease. The quoted sentences say what the papers report.
colorectal cancer (14 papers, 2020 to 2025). A primary or metastatic malignant neoplasm that affects the colon or rectum. "YTHDF1 is significantly associated with metastatic gene signatures through ARHGEF2 translation and RhoA signaling activation in colorectal cancer." (PMID 39185313, 2024). "Expression of ARHGEF2–219 is restricted to differentiated epithelia and lost in colorectal cancer cell lines, which instead express the shorter ARHGEF2-201 isoform." (PMID 41510227, 2025). "Consistently, a recent study reported that YTHDF1 regulates CRC tumorigenesis and metastasis by promoting ARHGEF2 translation and RhoA signaling in colorectal cancer." (PMID 36347025, 2022). "In addition, YTHDF1 escalates the translation of ARHGEF2, activating RhoA signaling, thereby driving tumorigenesis and metastasis in colorectal cancer." (PMID 40251202, 2025). "Similarly, YTHDF1 promotes ARHGEF2 translation in an m6A-dependent manner and promotes progression of colorectal cancer through RhoA signaling." (PMID 37259333, 2023). "Also, the Rasal3 mutation causes a unique susceptibility to colitis-associated colorectal cancer phenotype not seen in the Ccdc88b or Arhgef2 mutants." (PMID 38200184, 2024). "YTHDF1 serves an oncogenic role in colorectal cancer (CRC) through binding to m 6A sites of Rho guanine nucleotide exchange factor 2 (ARHGEF2) mRNA and promoting the translation of ARHGEF2." (PMID 40483535, 2025).
breast carcinoma (9 papers, 2012 to 2024). "Recent studies have underlined the oncogenic role of ARHGEF2 in promoting breast cancer cell invasion and metastasis and in the brain metastatic behavior of melanoma cells." (PMID 36335093, 2022). "Disruption of ARHGEF2/RHOA signaling (removal of BNIP-2 scaffold) affects breast carcinoma cells migration." (PMID 38200184, 2024). "Interestingly, expression of ARHGEF2 accelerates breast cancer invasion and metastasis." (PMID 31819039, 2019).
pancreatic cancer (5 papers, 2017 to 2024). "Mirroring observations come from pancreatic cancer studies, according to which ARHGEF2 (also known as GEF-H1) is implicated in promoting cell growth and invasiveness." (PMID 39456519, 2024). "Rho guanine nucleotide factor 2 (ARHGEF2, also known as GEF-H1) was extracted from a public database as the gene associated with an ER of pancreatic cancer." (PMID 34064540, 2021). "Relieving the negative regulation of RREB1 on ARHGEF2 contributes to the migratory behavior of pancreatic cancer cells." (PMID 32210733, 2020). "RREB1 has been identified a negative regulator of RHO guanine exchange factor ARHGEF2 that is essential for the growth and survival of pancreatic cancer." (PMID 32210733, 2020). "Since activating mutations of KRAS are found in over 90% of pancreatic cancers, we conjectured that oncogenic KRAS signaling would primarily regulate ARHGEF2 expression in PDAC cells." (PMID 27835861, 2017). "ARHGEF2 protein levels were found to correlate with tumor progression in pancreatic tumor specimens and are acutely elevated by inducible expression of RAS." (PMID 27835861, 2017). "The overexpression of ARHGEF2 is sufficient to increase ERK1/2 phosphorylation raising the possibility that the oncogenic potential of ARHGEF2 is partially mediated through its capacity to activate the MAPK pathway in pancreatic cancer." (PMID 36335093, 2022). "By relieving the negative regulation of RREB1 on the ARHGEF2 promoter, we determined that ETS1 and SP3 are essential for the normal expression of ARHGEF2 and contribute to the migratory behavior of pancreatic cancer cells." (PMID 27835861, 2017).
hepatocellular carcinoma (4 papers, 2022 to 2025). A malignant tumor that arises from hepatocytes. "Finally, ARHGEF2 overexpression has been associated with tumor progression including hepatocellular carcinoma, high-grade melanomas and malignant megakaryocytes." (PMID 38200184, 2024).
diffuse large B-cell lymphoma (3 papers, 2021 to 2024). "Research in diffuse large B-cell lymphoma highlights the direct regulation of ARHGEF2 by STAT3 in enhancement of cell migration." (PMID 39456519, 2024). "On the other hand, STAT3 supports amoeboid migration in diffuse large B-cell lymphoma (DLBCL), via ARHGEF2-RhoA signalling, whereby JAK inhibition reduces dissemination." (PMID 36699013, 2022).
Intellectual disability (3 papers, 2017 to 2022). "Here, we present evidence that the loss of function of Rho guanine nucleotide exchange factor 2 (ARHGEF2) causes a human neurodevelopmental disorder characterized by intellectual disability, mild microcephaly, and midbrain-hindbrain malformation." (PMID 28453519, 2017). "We identified, by means of whole exome sequencing, a homozygous frameshift mutation in the ARHGEF2 as a cause of intellectual disability, a midbrain-hindbrain malformation, and mild microcephaly in a consanguineous pedigree of Kurdish-Turkish descent." (PMID 28453519, 2017). "Specific RhoGEFs have been implicated in neurodevelopmental disorders, such as language impairment (ARHGEF19), intellectual disability (ARHGEF6, ARHGEF2), and moderate intellectual disability with speech delay (ARHGEF9)." (PMID 35959104, 2022). "In this study, we identified a frameshift mutation in the Rho guanine nucleotide exchange factor 2 gene (ARHGEF2) in two children presenting with intellectual disability, mild microcephaly, and a midbrain-hindbrain malformation." (PMID 28453519, 2017).
lung carcinoma (3 papers, 2017 to 2021). "Interesting, RALB was required for invasive lung cancer cell behavior through a mechanism dependent on ARHGEF2 activation of the RHOA/ROCK pathway." (PMID 27835861, 2017).
colitis (2 papers, 2024 to 2025). Inflammation of the colon. "Genetic ablation of Arhgef2-207 induces compensatory upregulation of Arhgef2-201, which is insufficient to restore barrier integrity, leading to spontaneous small intestinal inflammation and heightened susceptibility to colitis." (PMID 41510227, 2025). "Mice defective in Arhgef2 or Rasal3 show dampened neuroinflammation, and display altered cellular response and susceptibility to colitis; ARHGEF2 maps to a human Chromosome 1 locus associated with susceptibility to IBD." (PMID 38200184, 2024). "To better understand the susceptibility of Arhgef2−/− and Rasal3−/− mice to colitis, we conducted cellular immunophenotyping of colon cell populations by flow cytometry following DSS treatment." (PMID 38200184, 2024). "Taken together, these results indicate an altered response of Rasal3−/− and Arhgef2−/− mice to acute DSS-induced colitis, with higher susceptibility and increased pathology and enhanced inflammatory response." (PMID 38200184, 2024). "Conversely, Arhgef2 deficiency causes susceptibility to colitis, expressed as increased pathology score, increased production of inflammatory cytokines (IL6, MCP1, RANTES, C4b), increased infiltration of CD45+ cells in the lamina propria, with a marked abundance of CD11b+/Ly6G+ neutrophils." (PMID 38200184, 2024). "Interestingly, loss of Rasal3 or Arhgef2 also exacerbates the effect of DSS induced colitis." (PMID 38200184, 2024). "CCDC88B physically interacts with ARHGEF2 and RASAL3; defective mice show dampened neuroinflammation, altered susceptibility to colitis and altered DCs motility by modulating RHOA, with ARHGEF2 and RASAL3 acting in opposite regulatory fashions." (PMID 38200184, 2024). "To further investigate the contribution of lymphoid cells to the exacerbated colitis phenotype seen in Rasal3−/− and Arhgef2−/− mice, we tested the ability of B6, Rasal3−/− and Arhgef2−/− naïve CD4+ CD25−CD45RBHi T cells to induce colitis upon adaptive transfer into lymphopenic Rag1−/− mice." (PMID 38200184, 2024). "Hence, although mutations in Arhgef2 and Rasal3 have opposite effects on DC migration, they cause similar pathological effects in DSS-colitis, albeit with different leukocytes infiltrates." (PMID 38200184, 2024). "We therefore tested the response of Arhgef2−/− and Rasal3−/− mutant to DSS-induced colitis." (PMID 38200184, 2024). "Their functional interaction was established in vivo: Arhgef2−/− and Rasal3−/− mutants display resistance to neuroinflammation in EAE (alike Ccdc88bmut mice), and show altered inflammatory response during DSS induced colitis." (PMID 38200184, 2024).
Listeria infection (2 papers, 2019 to 2025). "Pol II CUT&Tag profiling revealed Listeria infection-specific changes in ARHGEF2 promoter usage." (PMID 41510227, 2025). "Promoter analysis demonstrates that Listeria infection did not significantly reduce ARHGEF2–219 promoter activation but enhanced activation of the specific promoter for the short ARHGEF2 isoforms." (PMID 41510227, 2025).
microcephaly (2 papers, 2017 to 2018). A congenital or acquired developmental disorder in which the circumference of the head is smaller than normal for the person's age and sex. "ArhGEF2 (also known as Lfc and GEF-H1) is a Rho GEF protein, and its loss of function is associated to a neurodevelopmental disorder characterized by ID, mild microcephaly and midbrain-hindbrain malformation." (PMID 29925821, 2018).
prostate carcinoma (2 papers, 2022). A carcinoma that arises from epithelial cells of the prostate gland. "We show that one of these genes, ARHGEF2, helps to maintain survival and neuroendocrine features in prostate cancer cells." (PMID 36159187, 2022). "Among the 95 NLS genes, the expression of ARHGEF2, LHX2, and EPHB2 is close associated with shortened disease survival in prostate cancer patients." (PMID 36159187, 2022). "Correspondingly, AR inhibition or AR antagonist treatment can restore ARHGEF2 expression, thereby allowing prostate cancer cells to induce treatment resistance and tolerance." (PMID 36335093, 2022). "ARHGEF2 promotes cell migration and invasion in gastric and prostate cancer via RhoA/ROCK activation." (PMID 36159187, 2022). "Among the 95 NLS genes, the expression of ARHGEF2, LHX2, and EPHB2 is close associated with clinicopathologic features and shortened disease-survival outcomes in prostate cancer patients." (PMID 36159187, 2022). "The data revealed that over 30% CRPC and over 15% NEPC patients harbored ARHGEF2 gene amplification status, but less than 5% in castration-sensitive prostate cancer patients." (PMID 36335093, 2022). "Taken together, these findings highlight the predominant role of ARHGEF2 in neuroendocrine differentiation in prostate cancer." (PMID 36335093, 2022). "Notably, genes downregulated by ARHGEF2 deletion were associated with critical pathways, namely, pathways in cancer, MAPK signaling pathway, central carbon metabolism in cancer and prostate cancer pathway." (PMID 36335093, 2022). "Besides, quantitative PCR and immunoblot analysis were also used to test whether DHT stimulation also inhibits ARHGEF2 expression in AR-negative prostate cancer cell lines (PC3 and DU145)." (PMID 36335093, 2022). "Collectively, these results suggest the potential of ARHGEF2, LHX2, and EPHB2 as indicators of poor survival for advanced prostate cancer." (PMID 36159187, 2022). "Lastly, further research, i.e., overexpressing ARHGEF2 in CRPC or enzalutamide-resistant models and using patient-derived organoids which harbor AR deletion, low AR activity or no AR expression models may be a more interesting way to demonstrate ARHGEF2 function in prostate cancer." (PMID 36335093, 2022).
cardiomyopathies (1 paper, 2024). "We identified further genes that regulate the development of trabeculation (NKX2-5, TBX20, HAND2, NRG1, NOTCH1 and DTNA) and those with evidence of involvement in cardiomyopathies (CRYAB and RIT1 (ARHGEF2))." (PMID 39567769, 2024).
cervical tumors (1 paper, 2021).
colorectal adenocarcinoma (1 paper, 2025). The most common type of colorectal carcinoma. "Importantly, ARHGEF2–219 expression was absent in human colorectal adenocarcinoma-derived cell lines Caco2, T-84, HCT116 and HT-29 that expressed the shorter ARHGEF2-201 isoform instead." (PMID 41510227, 2025).
endometritis (1 paper, 2020). An acute or chronic, usually bacterial infectious process affecting the endometrium. "However, earlier studies in cows with subclinical endometritis showed a decrease in ARHGEF2 expression, which will probably affect the gene profile of the embryo and its further development." (PMID 32708880, 2020).
febrile seizures (1 paper, 2008). "Similarly GEF is a synonym for ARHGEF2 gene (rho/rac guanine nucleotide exchange factor (GEF) 2), but it is also an acronym for generalized epilepsy with febrile seizures plus (GEFS+)." (PMID 19099596, 2008).
gastrointestinal stromal tumor (1 paper, 2017). "ARHGEF2 was one of multiple genes that displayed an altered response after treatment with Imatinib in gastrointestinal stromal tumors suggesting that targeting ARHGEF2 expression could be an attractive therapeutic treatment for susceptible cancer types." (PMID 27835861, 2017).
glioneuronal tumor (1 paper, 2022). "STRN1::NTRK2 and ARHGEF2::NTRK1 were reported in a single case of malignant glioneuronal tumor, respectively." (PMID 36531047, 2022).
inflammatory bowel disease (1 paper, 2024). A spectrum of small and large bowel inflammatory diseases of unknown etiology. "It should be noted that ARHGEF2, the gene encoding GEF-H1, maps to a human chromosome 1 locus associated with susceptibility to inflammatory bowel disease 35,36." (PMID 39483916, 2024).
intestinal cancer (1 paper, 2025). "Collectively, these findings reveal that differentiated intestinal epithelial cells express long ARHGEF2 isoforms that are lost in intestinal cancer cell lines, which instead express only the shorter ARHGEF2 variants." (PMID 41510227, 2025).
liver cancer (1 paper, 2022). An epithelial or non-epithelial malignant neoplasm that arises from the liver. "Further experiments showed that ARHGEF2 was highly expressed in liver cancer and was associated with malignant progression and poor prognosis." (PMID 35896520, 2022). "Notably, our study also suggested for the first time that ARHGEF2 promotes liver cancer-related angiogenesis." (PMID 35896520, 2022).